LEP (leptin)
Diseases named in the same sentence as LEP in open-access papers (continued):
Sharing a sentence is not in itself a finding about the gene and the disease.
cancer (continued). "Therefore, leptin produced by adipocytes and cancer cells could act in an autocrine and paracrine manner to promote proliferation, migration, survival, invasion and proinflammatory processes in tumor cells, and tumor angiogenesis." (PMID 28659656, 2017). "Besides storing excess calories in the form of lipids, the adipose tissue participates through diverse forms in the development of cancer due to the fact that it also acts as an endocrine gland, liberating the adipocytokines leptin and adiponectin and proinflammatory molecules." (PMID 29311755, 2017). "Finally, to account for competing risks, we ran Fine and Gray regression to estimate cumulative mortality of cancer over time with levels of leptin or CRP as the predictor variable and deaths from major cardiovascular diseases and other causes as competing outcomes." (PMID 26632325, 2016). "In addition to adipose tissue, leptin is expressed and secreted by some cancer cell types." (PMID 27472371, 2016). "Finally, abnormal levels of leptin and CRP may occur secondary to cancer which may result in reverse causation." (PMID 26632325, 2016). "Here, we show that a specific miRNA, miR-4443, responds to leptin and insulin treatment in CRC-derived cells and that its impaired regulation may contribute to deregulation of downstream signaling, increased cancer metastasis and worse prognosis in a state of leptin resistance." (PMID 27842582, 2016). "Furthermore, NILCO could be actively involved in leptin-induced cancer stem cell maintenance and drug resistance to chemotherapeutics." (PMID 27472371, 2016). "Similarly, there are several recent reviews detailing candidate mechanisms by which leptin and adiponectin could be impacting various aspects in the development of cancer in an integrated manner." (PMID 26132992, 2015). "Furthermore, NK cells in obese showed a non-significant altered proliferation process suggesting leptin as a possible link between bodyweight, lower NK cell functionality and herewith increased cancer susceptibility in obese humans." (PMID 26217516, 2015). "However, additional studies are necessary to determine the sources of leptin in the adipose tissue and whether leptin secreted by the obASCs utilizes similar signal transduction pathways to promote the survival of cancer cells." (PMID 26286584, 2015). "Ghrelin levels were significantly higher in cancer patients than in healthy subjects (573.31 ± 130 vs 320.20 ± 66.48 ng/ml, p < 0.0001), while obestatin (17.42 ± 7.12 vs 24.89 ± 5.54 ng/ml, p < 0.0001) and leptin (38.4 ± 21.2 vs 76.28 ± 17.48 ng/ml, p < 0.0001) values were lower." (PMID 25400234, 2014). "Therefore, an increased leptin level may contribute to cancer anorexia by preventing the normal compensatory mechanisms that should occur with decreased food intake." (PMID 24624094, 2014). "Thus leptin antagonists hold potential for future therapeutic use in cancer." (PMID 24587106, 2014). "Therefore, this paracrine-autocrine leptin axis could become a target for leptin-inhibiting drugs in cancer treatment and prevention." (PMID 25866478, 2014). "The blockade of central actions of leptin by systemic delivery of nanobody may compromise its anticancer effect, underscoring the need to develop peripherally acting leptin antagonists coupled with efficient cancer-targeting delivery." (PMID 24587106, 2014). "Moreover, leptin at high doses appears to reduce the effectiveness of different cancer treatments." (PMID 23554900, 2013). "For instance, mitogenic actions of leptin in certain organs in both normal and disease states have been reported and increasing epidemiological data in humans, as well as numerous in vitro investigation and animal studies suggest a link between leptin and cancer growth." (PMID 22690216, 2012).
cancer (continued). "Experimental data reveal that leptin may stimulate—through activation of cellular signal transduction pathways—cell growth, inhibit apoptosis processes, and induce migration processes and angiogenic factor expression in numerous cancer types." (PMID 22363883, 2011). "Leptin also stimulates growth and inhibits apoptosis of cancer cells, and may contribute to the increase in the incidence of different types of cancers that are observed in obese individuals, through the activation of JAK2-linked PI3K/Akt and MEK/ERK1/2 pathways." (PMID 21070531, 2010). "However, only the concentrations of VEGF, and leptin but not midkine, are associated with weight loss in the examined cohort of cancer patients." (PMID 20920199, 2010). "Hence, leptin may play an important role in controlling the proliferation, survival, and migration of cells involved in cancer growth." (PMID 19531256, 2009). "Taken together, as leptin has been associated with cancer risk, but has not been shown to be oncogenic, further studies are needed to elucidate the levels of leptin that are needed in human breast tissue for the development of cancer." (PMID 19223908, 2009). "Leptin and adiponectin, the most abundant adipocytokines produced by adipocytes and the best studied members of this family, stimulate growth, migration and invasion of cancer cells in vitro, thus displaying a capacity for promoting malignant biological behavior of cancer." (PMID 20030801, 2009). "Leptin may act as a growth factor in cancer, including the epithelial cancers of colon and breast." (PMID 17010200, 2006). "Leptin is a protein produced mainly by adipose tissue and may represent a growth factor in cancer." (PMID 17010200, 2006). "A key finding of this study is that leptin drives EMT via STAT3 activation, a central event in cancer metastasis, evidenced by decreased E-cadherin levels and cytoskeletal alterations." (PMID 41562922, 2026). "Tumor‐associated fibroblasts (CAFs) contribute to this process by secreting fatty acids and lipid‐related factors, such as leptin and tumor necrosis factor‐α (TNF‐α), which indirectly enhance cancer cell survival and angiogenesis." (PMID 40391753, 2025). "Ghrelin, in particular, is implicated in tumor advancement and reduced survival rates, while leptin is known to stimulate the production of pro-inflammatory cytokines TNF-α and IL-6, thereby facilitating cancer cell proliferation." (PMID 39980544, 2025). "Leptin can also induce the expression of vascular endothelial growth factor (VEGF), thus promoting angiogenesis, which is essential for cancer growth." (PMID 40558305, 2025). "Additionally, leptin may act as a modulator of innate and adaptive immune responses in cancer." (PMID 40227577, 2025). "Additionally, it has been suggested that leptin levels may play a role in some cancer types." (PMID 39789177, 2025). "These included Wnt, leptin, epidermal growth factor (EGF) receptor and transforming growth factor β (TGFβ) receptor pathways, all well-known for their roles in various carcinomas including stomach, colorectal and SRCC." (PMID 39910169, 2025). "In contrast to leptin, adiponectin is involved in the reversal and inhibition of the EMT, thereby playing a role in preventing cancer progression." (PMID 38255203, 2024). "Several cytokines, including leptin, IL-1B, IL-6, IL-8, IL-23, IL-17, and IL-10, stimulate cancer progression, while others, including IL-2, IL-12, and IFN-γ, inhibit cancer proliferation and/or invasion." (PMID 37979099, 2024). "The BMI effect on IL-6 and leptin is consistent with the BMI effect on TNBC invasiveness, given that these two adipokines can stimulate TNBC cancer cell migration and invasiveness." (PMID 39408921, 2024). "AT releases higher levels of adipose-derived cytokines, such as leptin, Interleukin-6 (IL-6), and CC-chemokine ligand 5 (CCL5), promoting cancer proliferation and invasion." (PMID 38800384, 2024).
cancer (continued). "Leptin–VEGF crosstalk supports the progression of cancer disease through the migration and invasion of cancer cells." (PMID 37686525, 2023). "Thus, targeting Leptin-LepR signaling may represent a novel strategy for cancer therapeutics." (PMID 37650871, 2023). "Leptin is known to activate a variety of signalling pathways, in particular the JAK2/STAT3 pathway included in these cancer cells." (PMID 37238197, 2023). "Leptin and IL-6 stimuli are known to promote the expression of pro-survival factors such as the B-cell lymphoma-2 (BCL-2) in cancer cell lines." (PMID 38068717, 2023). "PE (18:2-19:1) significantly stimulated the proliferation, migration and invasion of 4T1 and MDA-MB-231 cancer cells in a dose-dependent manner, suggesting the pro-tumour effect of PE mediated by miR-204/VHL mediated leptin signalling pathway." (PMID 37620316, 2023). "Atorvastatin reduced leptin-induced Akt signaling in OE33 cells, presenting a viable option for leptin modulation and cancer interception." (PMID 37511077, 2023). "Administration of an FASN inhibitor to obese cancer patients with T2D, NAFLD, and pronounced leptin insufficiency, however, should take into account the possibility of an induced deterioration of glycemic control and liver function." (PMID 37681411, 2023). "Our data indicate that fasting enhances the ability of CBIs to lower cholesterol in cancer cells and that this effect is dependent on fasting-mediated reduction in insulin, IGF1 and leptin." (PMID 37907500, 2023). "Activation of ObR by leptin overexpression mediates inflammation, VEGF/VEGFR-2-dependent angiogenesis and, by so doing, cancer progression." (PMID 38152619, 2023). "Immunohistochemical analysis showed that 6 gene (NLRX1, AKT1, CSRP1, LEP, MUC4 and SEMA4B) of 10 genes were abnormal expressions between cancer and paracancer tissue." (PMID 36817485, 2023). "Aromatase is induced in adipocytes by pro-inflammatory factors (such as IL6, TNFα) and adipokines (such as leptin), secreted by the adipocytes themselves, or by other cytotypes in the TME, including inflammatory cells and cancer cells themselves." (PMID 37561190, 2023). "In conclusion, the positive rate of LEP and LEPR expression in BC tissues was significantly higher than that in benign breast tissues and normal para-carcinoma tissues." (PMID 36941557, 2023). "The high level expression of LEP and LEPR in BC tissues were significantly higher than that in benign breast tissues and in para-carcinoma tissues (all P < 0.05)." (PMID 36941557, 2023). "LEP and LEPR were examined in BC tissues, benign breast tissues, para-carcinoma tissues using immunohistochemical staining." (PMID 36941557, 2023). "Previous studies in other cancer contexts, like BC and CRC, placed leptin, resistin, adiponectin, oncostatin, and osteopontin in the spotlight." (PMID 35875143, 2022). "Although its role in cancer remains controversial (as previously explained), TNF-α has been shown to play a key role in the pathogenesis of NHL and may increase the risk of disease together with leptin, especially in FL and DLBCL, through polymorphisms in the TNF rs1800629G>A gene." (PMID 36555171, 2022). "In our previous study, we observed that LLC cancer cell implantation into ND-fed lean C57BL/6 mice appeared to have a negligible effect on circulating levels of glucose, insulin and leptin." (PMID 36012397, 2022). "In children with cancer, changes in the level of gastrointestinal peptides such as CCK, ghrelin, leptin, and GLP-1 are also observed." (PMID 35563548, 2022). "Another pathway involved in cancer progression is nuclear factor-kappaB inducing kinase (NIK)/IKB kinase (IKK), and leptin-induced NIK/IKK phosphorylation inhibits cancer cell apoptosis in carcinoma cells." (PMID 36578551, 2022). "A significant interplay among leptin and IGF-I signaling has been suggested in cancer cells which synergistically increase the activation of EGFR and LEPR and mediate TNBC progression." (PMID 36077676, 2022).
cancer (continued). "Accumulating evidence showed that leptin is upregulated in GBC cell, and overexpression of leptin promotes cancer cell proliferation." (PMID 35111566, 2022). "For the purpose of meta-analysis, proteomic markers were classed as cancer antigens (CA-15.3, CA-19.9, CA-72.4, CEA), hormones (leptin, visfatin, prolactin) and other proteomic markers (G-CSF, YKL-40 and DJ-1)." (PMID 36230588, 2022). "Among them, ADPN, LEP, Visfatin, Resistin, Vaspin, Cytokines (e.g., NFkB, TNFα, IL6) and Progranulin (PGRN) have been related with cancer promotion." (PMID 34066328, 2021). "Moreover, up-regulation of autophagic process and inflammasomes activity, stimulation of cancer stem cell self-renewal, and promotion of epithelial-mesenchymal transition have recently been suggested to be partly responsible for the tumor-promoting effects of leptin." (PMID 33535537, 2021). "Upon binding to its receptor ObR, leptin activates JAK2/STAT3, MAPK, and PI3K/Akt signaling pathways to promote cell proliferation, hence acting as a growth-factor in cancer and involved in regulating tumor development, growth, and metastasis." (PMID 34485137, 2021). "This provides us with a hint that LEP G19A polymorphism may not lead to cancer by gaining weight." (PMID 34868961, 2021). "It is also worthy to note that leptin appears to promote fatty acid β-oxidation (FAO)-dependent energy production, since leptin was found to induce FAO in multiple cancer-related contexts." (PMID 33535537, 2021). "For the fatty acid metabolism, leptin has been shown to upregulate CD36, a scavenger receptor functioning as a transporter of long‐chain fatty acids, in various normal and cancer cells, which in turn facilitates uptake of exogenous fatty acids." (PMID 33226729, 2021). "Here, we especially focus on adipokines such as leptin, adiponectin, IL-6, and autotoxin (ATX), whose impaired secretions from CAAs promoted the cancer aggressive phenotype." (PMID 33917351, 2021). "The signaling pathways and gene expressions modulated by leptin and OB3 were investigated in different cancer cell lines." (PMID 34356668, 2021). "Cancer cells release leptin and express leptin receptor (LEPR), which suggests that leptin/LEPR signalling plays roles in tumour progression." (PMID 33397392, 2021). "It relays the molecular crosstalk to mediate the development of hallmarks of cancer, directly via its target genes such as IGF2, CD18, VEGF, FN1, GLUT1 and BCL2 and indirectly by inducing other factors such as insulin, leptin and negatively regulating PTEN." (PMID 34225729, 2021). "In vitro studies have demonstrated that leptin was able to activate ERK1/2 and c-Jun NH2-terminal Kinase (JNK) pathway and so promote cancer cell proliferation." (PMID 34354670, 2021). "However, given that leptin stimulation may affect many other possible metabolic processes, including improved mitochondrial function and decreased glucose‐dependent energetic production, other metabolic pathways could be included in the growth of cancer cells by leptin." (PMID 33226729, 2021). "According to the top 25 over/underexpressed genes for each type of cancer, LEP and NEGR1 were found to be extremely important in the occurrence of BRCA and BLCA cancer." (PMID 33299884, 2020). "Cancer cells have been shown to produce leptin and leptin receptor (LEPR), which strongly indicates the existence of a leptin-induced signaling pathway in the proliferation of cancer cells." (PMID 32742493, 2020). "Leptin and NILCO signaling mediate the activation of cancer stem cells that can affect drug resistance." (PMID 32471192, 2020). "The insulin-, the IGF-1-, and the leptin-induced signaling cascades converge on activation of PI3K/AKT-mTOR pathway, which stimulates cancer cell proliferation and survival, the latter being also stimulated by the estrogen-induced CDK4/6." (PMID 33271979, 2020).
cancer (continued). "Another study revealed that leptin provoked the JAK1/2, STAT3, FAK, ERK, and GSK3αβ signaling cascade to stimulate the production of soluble ICAM-1 in cancer cells, which induced osteoclast formation and enhanced tumor-induced osteolysis in vivo." (PMID 33371368, 2020). "Taken together, these data demonstrated that leptin was a biomarker of total and central adiposity in SCBT and in non-cancer controls." (PMID 32170116, 2020). "Leptin correlated strongly with total (p < 0.001) and central (WHR p = 0.001; WHtR p < 0.001) adiposity in SCBT and non-cancer controls." (PMID 32170116, 2020). "All these characteristics demonstrate the significant role of leptin as a new and dynamic actor driving EMT and functional consequences in cancer." (PMID 33334030, 2020). "Leptin synergizes with and even increases the levels of VEGF in various cancers, probably through MAPK- and PI3K-mediated upregulation of IL-1." (PMID 33316976, 2020). "This is followed by CFTR (18 cancer types) and four other genes that were amplified in 17 cancer types (ADIPOR2, LEP, PRKAG2 and RHEB)." (PMID 32807122, 2020). "Leptin signaling upregulates Notch and its gatekeeper, the transcription factor RBP-Jk, and several pluripotent molecules that can induce cancer stem cell maintenance." (PMID 32471192, 2020). "It is also known that BC cells overexpress leptin and its receptor, OBR, which has been highlighted as a marker for the stimulation of cancer cell survival and progression." (PMID 32471192, 2020). "Although the involvement of leptin and its receptors in GBM has been reported, the relationship between leptin and Notch signaling and their role in sustaining cancer stem cell activity in GBM remain to be completely unraveled." (PMID 32526957, 2020). "We demonstrate that leptin was a robust biomarker of total and central adiposity in SCBT, and that this trend was similar to the one noted in the non-cancer control group." (PMID 32170116, 2020). "In this study, our data showed that leptin stimulated the phosphorylation of STAT3 and the translocation of p-STAT3 to the nucleus of cancer cells." (PMID 33371368, 2020). "Accordingly, inhibition of insulin, IGF-1, and leptin by fasting can co-operate with blockade of estrogen and CDK4/6 to abrogate cancer cell proliferation and survival." (PMID 33271979, 2020). "We used multivariable linear regression analysis to determine if leptin predicts adiposity in SCBT and adjusted for age, sex, puberty, and cancer status." (PMID 32170116, 2020). "To determine if leptin levels were different between SCBT and non-cancer controls, we measured plasma leptin levels using Enzyme Linked Immunosorbent Assay (ELISA) technique." (PMID 32170116, 2020). "Together, these findings demonstrate that leptin is a key biomolecule that drives EMT and metastasis in cancer." (PMID 33334030, 2020). "BMA secrete various adipocytokines such as leptin, adiponectin, IL-1β, IL-6, vascular cell adhesion molecule 1 (VCAM-1), TNF-α, and VEGF, which influence cancer cell biology." (PMID 31334678, 2019). "And C-reactive protein, adiponectin, and leptin play an important role in inflammatory environment that are related to SUA and cancer." (PMID 31885729, 2019). "Thus, the use of leptin antagonist could be a useful therapeutic strategy against cancer." (PMID 31141984, 2019). "If MMP-2 and MMP-9 participate in leptin-dependent migration via FAK activation, their secretion must be controlled by a similar signaling pathway that controls migration of cancer cells." (PMID 31671408, 2019). "A possible explanation for the decrease in leptin levels with higher fatigue levels could be that an adaptive reduction of energy expenditure has been induced, resulting in increased appetite in response to metabolic impairment induced by cancer‐related inflammation." (PMID 31016867, 2019). "For example, several previous studies have demonstrated that leptin is an upstream regulator of VEGF expression in endothelial and cancer cells." (PMID 30792482, 2019).